CRP (C-reactive protein)
Diseases named in the same sentence as CRP in open-access papers (continued):
Sharing a sentence is not in itself a finding about the gene and the disease.
amyloidosis (25 papers, 2010 to 2025). A disorder characterized by the localized or diffuse accumulation of amyloid protein in various anatomic sites. "There was a inverse association between C-reactive protein and amyloidosis and an positive causal relationship between C-reactive protein and aortic atherosclerosis." (PMID 40779499, 2025). "Although classically recognized as a marker of acute inflammation, CRP is increasingly implicated in the pathogenesis of protein-misfolding pathologies, notably neurodegenerative diseases and amyloidosis." (PMID 40534869, 2025). "Whereas amyloidosis onset was associated with reduced C-reactive protein levels (IVW:p = 0.022, OR=0.582,95% CI:0.366–0.924)." (PMID 40779499, 2025). "A number of studies have shown that elevated CRP is linked to AS and reduced CRP is linked to amyloidosis." (PMID 40779499, 2025). "We assessed the association of C-reactive protein on amyloidosis by Mendelian randomization analysis, which can provide better support and ideas for subsequent research and treatment of this disease." (PMID 40779499, 2025). "In our study, the presence of the homozygous M694V mutation in FMF patients, along with PIV and CRP levels determined during the attack-free period, emerged as independent risk factors for predicting both amyloidosis and moderate-to-severe disease." (PMID 38535054, 2024). "In our study, CRP proved to be an independent risk factor for the prediction of both amyloidosis and moderate-to-severe disease." (PMID 38535054, 2024). "SAA, ESR and CRP are good indicators of disease activity and response to treatment of the underlying disease that cause amyloidosis." (PMID 28558744, 2017). "A previous study has shown an association between CRP and amyloidosis." (PMID 40779499, 2025). "Therefore, this Mendelian randomization study aims to explore the specific causal association between CRP and amyloidosis and between CRP and AS." (PMID 40779499, 2025). "Notably, the present study found that CRP reduced the risk of amyloidosis, and the correlation was a 41.8% reduction in the risk of amyloidosis (OR=0.582)." (PMID 40779499, 2025). "Methodologically, the innovative use of Mendelian randomization analysis overcomes issues in traditional studies, enabling us to establish a causal link between low CRP levels and amyloidosis, which, despite differing from previous findings, provides new research perspectives." (PMID 40779499, 2025). "In amyloidosis, patients’ CRP levels change significantly, and CRP has a reference value for assessing the disease condition." (PMID 40779499, 2025). "This study, using European-sourced samples, has its limitations in generalizability but offers a unique chance to explore the CRP-amyloidosis relationship in this specific population." (PMID 40779499, 2025). "In multivariate analysis, PIV, C-reactive protein (CRP), and the presence of the M694V homozygous mutation emerged as independent risk factors for both amyloidosis and moderate-to-severe disease." (PMID 38535054, 2024). "In particular, in the presence of M694V homozygotes, patients with elevated CRP and a PIV ≥ 518.1 cut-off in the attack-free period should be closely monitored for the risk of amyloidosis and moderate-to-severe disease." (PMID 38535054, 2024). "FMD percentage was significantly lower, and CRP levels significantly higher in CVD positive patients with FMF-related amyloidosis than those with GN (p = 0.004 and p = 0.020, respectively)." (PMID 33110219, 2020). "We sincerely thank Professor Mark B. Pepys, Centre for Amyloidosis and Acute Phase Proteins, University College London for giving us valuable human CRP and SAP with pertinent advice." (PMID 27380955, 2016). "In view of the fact that amyloidosis lesions are intricately related to the aggregation and fibril formation of amyloid peptides, the anti – amyloidogenic property of CRP, as revealed by these results, suggests that CRP can inhibit the development of amyloidosis." (PMID 40779499, 2025).
amyloidosis (continued). "In patients with FMF, especially in the presence of the M694V homozygous mutation, CRP and PIV may be useful in predicting both amyloidosis and moderate-to-severe disease." (PMID 38535054, 2024). "In summary, our results validate the negative association between CRP and amyloidosis and the positive association between CRP and AS, which may provide valuable information for the clinical treatment and prevention of the corresponding diseases." (PMID 40779499, 2025). "Notably, our study found a negative effect of CRP on amyloidosis, i.e., CRP reduces the risk of developing amyloidosis, which is in line with speculations made in the previous study." (PMID 40779499, 2025). "Among FMF patients who received anti-IL-1 therapy, fibrinogen, NLR, and RDW, as well as inflammatory parameters such as ESR and CRP levels, were higher in patients with amyloidosis than those without amyloidosis." (PMID 38812979, 2022). "Cerebrospinal fluid levels of C-reactive protein and soluble TREM2 differed between nondemented subjects, patients with MCI, or patients with AD and were associated with amyloid and tau pathology." (PMID 29482610, 2018). "We cannot attribute this observed amyloidosis to inflammation, as CRP levels were normal." (PMID 20548961, 2010). "In this study, SAA measurement was not available, but median CRP and ESR values at the time of amyloidosis diagnosis were 4.0 mg/dl and 46 mm/hr, respectively." (PMID 40266382, 2025). "In a mouse model of amyloidosis, it has been shown previously that injected human SAP was deposited in amyloidotic mice while Li-CRP was not." (PMID 39351235, 2024). "In FMF patients with amyloidosis, the mean/median values of fibrinogen, ESR, CRP, WBC, neutrophil, NLR, and RDW were significantly higher than those without amyloidosis (p < 0.05)." (PMID 38812979, 2022). "Within the FMF patient group, the ESR, CRP, fibrinogen, RDW, and NLR values were significantly higher in the subgroup with amyloidosis in comparison to the subgroup without amyloidosis." (PMID 38812979, 2022). "When only the FMF patients with or without amyloidosis were considered, in patients who received anti-IL-1 therapy, the fibrinogen level, RDW, and NLR, as well as inflammatory parameters such as ESR and CRP, were higher in patients who had amyloidosis than those who had not." (PMID 38812979, 2022).
aortic stenosis (25 papers, 2006 to 2026). Aortic valve stenosis is a aortic valve disease caused by the incomplete opening of the aortic valve. "It was reported that CRP rs1205 polymorphism is associated with elevated CRP levels in Aortic stenosis patients and cardioembolic stroke." (PMID 36448063, 2022). "It was demonstrated that serum CRP levels predict progression and severity of aortic stenosis due to the pathogenic role of inflammation on valvular disease." (PMID 32549101, 2020). "Wypasek and colleagues reported that IL-6R single nucleotide polymorphisms were associated with mean concentrations of C-reactive protein among patients with aortic stenosis." (PMID 26714766, 2015). "One study found that the minor allele of the rs1205 CRP polymorphism could serve as a potential marker in identifying subjects prone to severe and heavily calcified aortic stenosis." (PMID 27386381, 2016). "Background and Objectives: This study investigated the prognostic value of the C-reactive protein-albumin-lymphocyte (CALLY) index in predicting all-cause mortality among patients undergoing transcatheter aortic valve implantation (TAVI) for severe aortic stenosis." (PMID 42075625, 2026). "Moreover, several studies have shown that mechanical shear stress, such as that observed in aortic stenosis, can cause the dissociation of pentameric CRP into its monomeric form, highlighting a potential mechanosensory pathway that links physical stress to inflammatory activation." (PMID 41373439, 2025). "Among patients with severe aortic stenosis (AS), we investigated the associations of N–terminal pro–natriuretic peptide (NT–proBNP), high–sensitive troponin T (hsTnT), and high–sensitive C–reactive protein (hs–CRP) with 3–year mortality and major adverse cardiovascular events (MACE) during 1 year." (PMID 28604834, 2017). "A recent study revealed a novel mechanosensing function of CRP, showing that pathophysiological shear stress, such as that observed in aortic stenosis, can induce its dissociation into mCRP, which has potent proinflammatory and prothrombotic effects." (PMID 41373439, 2025). "A sub-study of the SEAS randomised controlled trial of lipid-lowering therapy in aortic stenosis showed a weak correlation between high sensitivity CRP rise and progression of AS." (PMID 35355968, 2022). "In previous studies, increased CRP value was found to be related with poor prognosis in patients with severe aortic stenosis." (PMID 32549101, 2020). "It means that increased serum CRP levels are related with progression, severity, and prognosis of aortic stenosis." (PMID 32549101, 2020). "Inflammation is an important process in aortic stenosis development and various studies showed correlation between CRP levels and other inflammatory markers and aortic stenosis in patients with CKD." (PMID 32160250, 2020). "Subjects who developed aortic stenosis during follow-up had a higher mean age at baseline (54.4 vs 44.6) and a higher proportion of males, as well as higher fasting glucose, lipid levels, apoB/apoA-1 ratio and CRP." (PMID 39915078, 2025). "Rivaroxaban reduced valvular calcium deposits, aortic stenosis, and CRP levels." (PMID 40870420, 2025). "Age, physical activity, C-reactive protein, and serum albumin levels—but not progressive aortic stenosis—predicted all-cause mortality." (PMID 34513029, 2021). "While the detailed pathogenesis of aortic stenosis is still unclear, higher C-reactive protein as an acute phase protein may indicate a more active state of inflammation being part of the pathogenesis, resulting in a possible higher cardiovascular risk profile." (PMID 38252146, 2024). "High-sensitivity troponin T (hs-TnT) and high-sensitivity C reactive protein (hs-CRP) may convey prognostic information in patients with aortic stenosis (AS)." (PMID 33051334, 2020). "This showed that, despite favorable changes in lipid parameters and C-reactive protein levels, the progression of aortic stenosis was not influenced." (PMID 40870420, 2025).
aortic stenosis (continued). "Serum CRP is also elevated in patients with asymptomatic aortic stenosis, does not rise in accordance with increasing severity of valvar disease, and decreased from before to 6 months after aortic valve replacement." (PMID 16774687, 2006).
aspiration pneumonia (25 papers, 2010 to 2025). "Previously, we have demonstrated that high CRP levels were significantly associated with in-hospital mortality among patients with aspiration pneumonia." (PMID 38525743, 2024). "Elevated CRP levels before tracheostomy suggested inflammation, possibly due to aspiration pneumonia." (PMID 40786461, 2025). "It has been reported that decannulation is difficult in cases of aspiration pneumonia with CRP elevation." (PMID 40786461, 2025). "Aspiration pneumonia induces muscle atrophy in the respiratory, skeletal, and swallowing systems via the expression of pro-inflammatory biomarkers such as C-reactive protein and IL-6." (PMID 39311243, 2024). "The study results show that the resolution of LUS abnormalities and CRP levels most closely follow the clinical picture of aspiration pneumonia." (PMID 39614316, 2024). "Aspiration pneumonia occurs in 20–60% of critically ill patients and CRP increases more rapidly within the first 48 h in patients with aspiration pneumonia." (PMID 35208646, 2022). "Furthermore, typical complications in HNSCC patients, such as aspiration pneumonia, can falsify the evaluation of CRP as interim acute inflammatory phases as well." (PMID 39001486, 2024). "Higher levels of CRP and PCT at the time of intubation were significantly associated with difficulty in oral intake, suggesting that patients with bacterial infections or aspiration pneumonia before intubation tend to have a longer duration of mechanical ventilation and dysphagia." (PMID 38514734, 2024). "CRP levels may predict disease progression as well as the development of aspiration pneumonia." (PMID 38525743, 2024). "One published study used a sliding protocol to evaluate aspiration pneumonia in 17 dogs with AP, combining LUS findings with TXR, C-reactive protein (CRP) levels, and clinical abnormalities." (PMID 39614316, 2024). "CRP levels tend to rise shortly after birth in neonates with MAS, potentially in response to chemical pneumonitis, mechanical ventilation, bacterial superinfection, and airway obstruction." (PMID 34408219, 2021). "Her serum C-reactive protein (CRP) was mildly elevated to 6.6 mg/dL and chest computed tomography showed mild aspiration pneumonia in the left S10 segment of left lung." (PMID 34102997, 2021). "The significantly lower levels of CRP and PCT observed in the TG after the intervention provide laboratory-based, quantitative evidence supporting the reduced incidence of clinically diagnosed aspiration pneumonia." (PMID 41438699, 2025). "Together with our results, these findings suggest that patients with higher levels of CRP and PCT may have dysphagia and aspiration pneumonia." (PMID 38514734, 2024). "Important confounders like aspiration pneumonia, ventricular drainage insertion with subsequent ventriculitis, or discoagulation might have an effect on the WBC count and CRP values, and might affect our results." (PMID 35208646, 2022). "Dogs in which CRP did not decrease, not only may have shown a lack of improvement in their intestinal inflammation, but also may have developed inflammation or infectious co‐morbidities, such as aspiration pneumonia." (PMID 38819636, 2024).
End Stage Liver Disease (25 papers, 2012 to 2025). Final stage of a liver disease when the liver failure is irreversible and LIVER TRANSPLANTATION is needed. "High alpha-fetoprotein (AFP), high C-reactive protein (CRP), low albumin, and an increase in Model for End-stage Liver Disease (MELD) and Child-Turcotte-Pugh (CTP) scores were found to have a negative impact at three months." (PMID 40385925, 2025). "Similarly, Gal-3 did not correlate with the degree of LF, viral load, viral genotype, CRP, leukocyte count, or the model for end stage liver disease (MELD) score in CHC69." (PMID 40316644, 2025). "In addition, the positive rate of bacterial DNA is significantly related to end-stage liver disease score, procalcitonin, C-reactive protein, and heart rate." (PMID 34858903, 2021). "Therefore, CRP levels may reflect the degree of translocation of bacteria in patients with end-stage liver disease." (PMID 34439862, 2021). "AXL expression on liver macrophages correlated negatively with disease severity scores (Child-Pugh and Model of End-Stage Liver Disease [MELD] scores) and a marker of inflammation (C-reactive protein)." (PMID 37004869, 2023). "The aspartate aminotransferase (AST) level, alanine aminotransferase (ALT) level, C-reactive protein (CRP) level, and model for end-stage liver disease (MELD) score were higher in patients with LC in the post-ACLF group compared with those in the non- and pre-ACLF groups." (PMID 36829443, 2023). "CRP: C-reactive protein, ALT: alanine aminotransferase, AST: aspartate aminotransferase, INR: international normalized ratio, CTP: Child-Turcotte-Pugh, MELD: model for end-stage liver disease." (PMID 33585129, 2021). "A multivariate proportional hazards model was created based on the tumor response, the number of tumor nodules, the score of the model for end stage liver disease (MELD), and the serum C-reactive protein levels which were independent predictors of survival in HCC patients at one month post-SIRT." (PMID 24367506, 2013). "In conclusion, this study reported that pre-transplantation CRP level was a novel and a potentially useful predictor of the 30-day CSI post-LT, and which positively correlated with the concentration of the bacterial product LPS in patients with end-stage liver disease." (PMID 34439862, 2021). "In addition, for all other parameters, including age, body weight, Child-Pugh score, model of end-stage liver disease (MELD) score, white blood cell count (WBC), C-reactive protein and medical treatment, no clear correlation with the level of ascites’ neutrophil function could be found." (PMID 27917877, 2016).
Hypercalcemia (25 papers, 2017 to 2026). An abnormally increased calcium concentration in the blood. "Similarly, hypercalcemia has been linked to heightened inflammatory states, including elevations in C-reactive protein and interleukin-6 levels." (PMID 41153752, 2025). "Laboratory investigations revealed chronic normocytic anemia, elevated C-reactive protein (CRP), hypercalcemia, hyperphosphatemia, and increased alkaline phosphatase (ALP)." (PMID 40535409, 2025). "Multivariable analysis revealed that CRP level (P = 0.002), grade (P = 0.032), hypercalcemia (P = 0.023) and hemoglobin level (P = 0.037) were independent predictors of LRG1 levels." (PMID 38658967, 2024). "Regarding clinical presentation, cases of ATLL with TFHP showed increased CRP levels and a tendency to develop hypercalcemia." (PMID 38506241, 2024). "High NLR was observed in patients with higher stage of the disease, with poor performance status, hypercalcemia, and high CRP." (PMID 32458064, 2020). "Laboratory tests revealed elevated ESR, as well as CRP, hypercalcaemia, and IgM paraproteinaemia." (PMID 40951148, 2025). "Significant correlations were observed between serum miR-16 expression levels and Cr (r = −0.473, p = 0.002), GFR (r = −0.466, p = 0.001), Cr ≥ 2 (r = −0.562, p = 0.002), hypercalcemia (r = −0.460, p = 0.003), B2M (r = −0.370, p = 0.021), and CRP (r = −0.356, p = 0.022)." (PMID 38892251, 2024). "This was the case for renal impairment, hypercalcemia, B2M, and CRP serum levels." (PMID 38892251, 2024). "Based on the analysis of patients with aggressive ATL, including those who received transplants, we identified five prognostic factors for poor outcomes: acute-type ATL, poor performance status, high soluble interleukin-2 receptor levels, hypercalcemia, and high C-reactive protein level." (PMID 31681185, 2019). "However,there was a persistent increase in C-Reactive Protein (CRP) of 11 mg/L (RV: < 8),which is an inflammatory marker; increasing proteinuria reaching 856.3 mg/24h in 60days of follow-up (RV: up to 150), hypercalcemia of 13.1 mg/dL (RV: 8.5-10.2) andhypercalciuria of 504.7 mg/24h (VR: 100-300)." (PMID 29944158, 2018). "In our study, 27% of patients with hypercalcaemia were diagnosed with cancer; the risk was even higher in hypercalcaemic patients with high levels of one of the following: lactate dehydrogenase (LDH), alkaline phosphatase, white blood cell count, CRP or platelet count." (PMID 29202799, 2017). "Biological workup revealed significant elevations in alkaline phosphatase (ALP), C-reactive protein (CRP), and erythrocyte sedimentation rate (ESR), alongside hypercalcemia." (PMID 40837938, 2025). "Investigations revealed neutrophilic leukocytosis, elevated C-reactive protein (CRP) and procalcitonin and hypercalcemia with a normal thyroid-stimulating hormone (TSH)." (PMID 37362540, 2023).